ZNF808 (zinc finger protein 808)
Description:
Transcriptional repressor that targets mainly transposable elements. Primarily targets the long terminal repeat of endogenous retroviruses classified as MER11 elements which comprise subfamilies A, B and C. May silence transposable elements through the establishment of heterochromatin-associated trimethylation of 'Lys-9' of histone H3 (H3K9me3). Can also bind to certain gene promoters and other genomic regions. Represses transcription of specific MER11 elements during differentiation toward pancreatic lineages in early pancreas development. By repressing transcription, prevents a liver gene expression program from being aberrantly activated during pancreas differentiation.
Synonyms: PAGEN3
Tractability: PROTAC: UniProt records ubiquitination sites on it; ubiquitination databases record sites on it.
Gene: Protein-coding gene on chromosome 19 (52,527,652 to 52,564,464, forward strand). Ensembl gene ENSG00000198482.
Subcellular location: Nucleus
Gene Ontology:
Molecular function: transcription cis-regulatory region binding; sequence-specific double-stranded DNA binding
Biological process: cell differentiation; negative regulation of gene expression; pancreas development; negative regulation of transcription by RNA polymerase II; regulation of DNA-templated transcription; regulation of gene expression
Cellular component: nucleus
Genetic constraint (gnomAD): Loss-of-function variants: 5 observed, 8.79 expected, observed/expected ratio (o/e) 0.57, 90% interval 0.3 to 1.19. That is too few expected variants to judge how well the gene tolerates losing a copy. Missense variants: 1,103 observed, 1,122.3 expected, observed/expected ratio (o/e) 0.98, 90% interval 0.94 to 1.03. Synonymous variants: 380 observed, 376.25 expected, observed/expected ratio (o/e) 1.01, 90% interval 0.93 to 1.1.
Homologues: Orthologues: macaque ZNF808 (80% identical), Drosophila melanogaster CG18476 (23% identical), Drosophila melanogaster CG10669 (20% identical). Paralogues in human: ZNF721 (39% identical), ZFP62 (37% identical), ZNF485 (21% identical), ZNF648 (17% identical), ZNF664 (15% identical).
Diseases named in the same sentence as ZNF808 in open-access papers:
ZNF808 is named in the same sentence as 12 diseases in open-access papers, as found by Europe PMC text mining. Sharing a sentence is not in itself a finding about the gene and the disease. The quoted sentences say what the papers report.
diabetes (5 papers, 2023 to 2026). "In 4 newly identified individuals with biallelic ZNF808 LoF variants the diabetes was reported to be transient: 1 individual had NDM (patient 11), 2 had infancy-onset diabetes (patients 9c, 12) and 1 had unspecified diabetes onset before 1 year (patient 10)." (PMID 41500078, 2026). "Biallelic loss-of-function ZNF808 variants were recently identified as a cause of pancreatic agenesis characterised by insulin-treated permanent neonatal diabetes (PNDM), low birthweight and exocrine pancreatic insufficiency." (PMID 41500078, 2026). "In this study, we explore the phenotypic spectrum caused by biallelic ZNF808 variants in a large cohort of individuals referred for monogenic diabetes testing." (PMID 41500078, 2026). "Our results suggest that testing for variants in the ZNF808 gene should be considered in individuals with diabetes diagnosed after the neonatal period, especially if born to related parents." (PMID 41500078, 2026). "Our study in a large monogenic diabetes cohort expands the phenotype resulting from ZNF808 LoF variants from PNDM and PA to infancy-onset, transient and adolescent-onset diabetes without exocrine pancreatic insufficiency." (PMID 41500078, 2026). "We also report an association between the position of variants within the ZNF808 protein and diabetes phenotype, indicating that variant-specific differences in protein function may account for some of the phenotypic variability seen in the cohort." (PMID 41500078, 2026). "This is not unexpected since these cohorts include only a small number of individuals with monogenic diabetes and biallelic ZNF808 variants were rare in our clinically selected cohort of individuals with adolescent/adult-onset monogenic diabetes (3/4170 individuals diagnosed after 1 year of age)." (PMID 41500078, 2026). "The significant clustering of ZNF808 variants in individuals with transient, infancy-onset and adolescent-onset diabetes in the latter half of the protein suggests that truncation in this region may lead to a greater degree of retained function, with a more variable effect on pancreas development." (PMID 41500078, 2026). "We report 17 additional individuals with ZNF808-diabetes, almost doubling the number of patients that have been described to date." (PMID 41500078, 2026). "ZNF808 gene testing should be considered in individuals with diabetes diagnosed after the neonatal period, especially if born to related parents." (PMID 41500078, 2026). "The majority of individuals with ZNF808 loss-of-function variants (19/31) had PNDM, however 12 individuals had other diabetes phenotypes: 5 infancy-onset diabetes, 4 transient diabetes and 3 adolescent-onset diabetes." (PMID 41500078, 2026). "This case illustrates the significant multisystem effects of ZNF808-related pancreatic agenesis and emphasizes the necessity of early genetic testing in infants with neonatal diabetes and EPI." (PMID 41393705, 2025). "Including the 13 previously reported cases in the Exeter cohort, this brings the total number of individuals with NDM caused by ZNF808 variants to 20, confirming that NDM is the most common diabetes phenotype associated with this genetic subtype (20/31, 64.5%)." (PMID 41500078, 2026). "None of these studies investigated the presence of ZNF808 variants in individuals with diabetes diagnosed after 6 months of age." (PMID 41500078, 2026). "Disease-causing ZNF808 variants were also not identified in individuals with diabetes in these population cohorts." (PMID 41500078, 2026). "This means that the relative frequencies of the different diabetes phenotypes observed in this study are not necessarily representative of the true distribution among individuals with bi-allelic ZNF808 variants." (PMID 41500078, 2026). "Individuals with ZNF808-diabetes did not always require insulin treatment, with sulphonylurea treatment reported in 3 individuals." (PMID 41500078, 2026).
diabetes (continued). "The spectrum of causative genes (PTF1A, GLIS3, WFS1, INSR, SLC29A3, ZNF808, ABCC8, INS) is markedly different from the monogenic diabetes genes seen in non-consanguineous cohorts, and also different from those seen in other consanguineous populations." (PMID 37897565, 2023). "The identification of biallelic variants among individuals diagnosed with diabetes in adolescence and individuals with non-insulin-treated diabetes has implications for treatment and genetic testing and indicates that inclusion of ZNF808 to genetic testing panels used for MODY should be considered." (PMID 41500078, 2026).
pancreatic agenesis (5 papers, 2023 to 2026). Partial agenesis of the pancreas is characterized by the congenital absence of a critical mass of pancreatic tissue. "Whole-genome sequencing identified a homozygous likely pathogenic variant in the ZNF808 gene, confirming a diagnosis of pancreatic agenesis-3." (PMID 41809312, 2026). "Loss-of-function variants in ZNF808 have recently been identified as a cause of pancreatic agenesis (PA), clinically defined as neonatal diabetes (NDM) diagnosed in the first 6 months of life and exocrine pancreatic insufficiency." (PMID 41500078, 2026). "The identified ZNF808 mutation has been documented in multiple unrelated cases of isolated pancreatic agenesis, supporting its pathogenicity." (PMID 41393705, 2025). "The constellation of radiographic findings demonstrating complete pancreatic agenesis, coupled with the genetic identification of a pathogenic ZNF808 mutation, provided definitive confirmation of congenital pancreatic agenesis as the unifying diagnosis." (PMID 41393705, 2025). "We report the identification of recessive loss-of-function variants in ZNF808, a primate-specific gene, as a cause of pancreatic agenesis, a congenital developmental disorder." (PMID 37973953, 2023). "Here, we report the identification of homozygous loss-of-function variants in the primate-specific gene ZNF808 as a cause of pancreatic agenesis." (PMID 37973953, 2023). "Overall, our findings show that ZNF808 biallelic loss-of-function variants cause pancreatic agenesis/neonatal diabetes." (PMID 37973953, 2023). "A homozygous protein-truncating mutation in a primate-specific gene, ZNF808 gene, was recently reported as a cause of pancreatic agenesis characterized by ND and exocrine pancreatic insufficiency (two of the three patients from our cohort were included in the original study)." (PMID 40302952, 2024). "Loss-of-function mutations in primate-specific ZNF808 cause pancreatic agenesis." (PMID 37973953, 2023). "The patients’ phenotype supports a role for ZNF808 in early pancreatic development affecting both endocrine and exocrine pancreatic functions (pancreatic agenesis)." (PMID 37973953, 2023). "Biallelic loss of ZNF808 results in a variable pancreatic phenotype ranging from pancreatic agenesis to adult-onset diabetes without exocrine insufficiency." (PMID 41500078, 2026). "Taken together, our data show that ZNF808 is essential to prevent a liver gene expression program from being aberrantly activated during pancreas differentiation, suggesting a potential mechanism for pancreatic agenesis." (PMID 37973953, 2023). "No deleterious homozygous loss-of-function ZNF808 variants were identified in >680,000 individuals without neonatal diabetes or pancreatic agenesis (UK BioBank (n = 454,756), Gnomad v.2.1.1 (n = 141,071), 100,000 genomes project from Genomics England (n = 75,118) and Genes and Health (n = 8,921))." (PMID 37973953, 2023).
exocrine pancreatic insufficiency (3 papers, 2024 to 2026). Inability of the exocrine pancreas to produce and secrete an adequate amount of digestive enzymes into the small intestine. "This case report describes a male infant with complete pancreatic agenesis due to a homozygous ZNF808 mutation, presenting with permanent neonatal diabetes mellitus (PNDM) and exocrine pancreatic insufficiency (EPI)." (PMID 41393705, 2025).
lung carcinoma (2 papers, 2023 to 2024). "We identified 7 DMRs corresponding to 7 differentially methylated genes (DMGs) including HOXB4, HOXA7, HOXD8, ITGA4, ZNF808, PTGER4, and B3GNTL1 that were highly associated with lung cancer by comparing the methylation profiles of lung cancer and benign nodule tissue." (PMID 37101220, 2023). "It turned out that the expressions of B3GNTL1 and HOXD8 were significantly upregulated, while the expression of remaining five genes (HOXB4, ZNF808, ITGA4, PTGER4, and HOXA7) were significantly downregulated in lung cancer tissues (p < 0.01)." (PMID 37101220, 2023).
maturity onset diabetes (1 paper, 2026). "The identification of biallelic variants among individuals with adolescent-onset diabetes has implications for genetic testing and indicates that ZNF808 testing should be considered in individuals with maturity onset diabetes of the young (MODY)." (PMID 41500078, 2026).
ZNF808 also shares sentences with these, for which no sentence is quoted: tumor (2 papers); Cerebellar hypoplasia (1); insulin-dependent diabetes (1); MODY (1); neonatal diabetes mellitus (1); Onset (1); renal hypoplasia (1).